APLP2 (amyloid beta precursor like protein 2)
Diseases named in the same sentence as APLP2 in open-access papers (continued):
Sharing a sentence is not in itself a finding about the gene and the disease.
cancer (continued). "We have found that APLP2 increases MHC class I internalization in HeLa cells, which suggests it may contribute to cancer immune evasion." (PMID 25576918, 2015).
tumor (23 papers, 2008 to 2026). "This study further clarifies the expression of APLP2 in macrophage subpopulations, in addition to expanding the knowledge of macrophage subtypes associated with the NB tumor environment and our understanding of APLP2’s role in macrophage physiology." (PMID 40265027, 2025). "Therefore, partial loss of the expression of another protein (i.e., PKCε) was also able to impact phenotype in a mouse tumor model to a similar extent as full loss, as we have seen with APLP2." (PMID 33810510, 2021). "In another study, evaluation of macrophage-related gene expression revealed that APLP2 is one component of a nine-gene prognostic signature in hepatocellular carcinoma patients, where an increased risk score correlated with higher tumor stage, tumor grade, and mortality." (PMID 40265027, 2025). "Evaluation of human mRNA data revealed that APLP2 is more highly expressed in human M2/anti-inflammatory (pro-tumor) macrophages than in M1 macrophages (which have a pro-inflammatory, anti-tumor phenotype)." (PMID 40265027, 2025). "Promoting mixed or M0/undifferentiated macrophages in preference to the anti-tumor M1/pro-inflammatory macrophages implicates a role for APLP2 in impeding an effective anti-tumor immune response." (PMID 40265027, 2025). "In the primary tumor, APLP2, BNIP3L, CD59 and DKK3 were highly expressed in 29.7% (n = 38), 64.9% (n = 83), 92.2% (n = 118) and 80.5% (n = 103), respectively." (PMID 35796776, 2023). "Our analysis of gene expression data from patient samples showed an increase in amyloid precursor-like protein 2 (APLP2) expression within primary tumor epithelium relative to pancreatic intraepithelial neoplasia (PanIN) epithelial cells." (PMID 33810510, 2021). "Upon imaging, it was apparent that the knockdown of APLP2 expression significantly inhibited tumor development." (PMID 25576918, 2015). "Examination of matched human primary tumor-liver metastasis pairs showed that 38.1% of the patients had positive APLP2 expression in both the primary tumor and the corresponding liver metastasis." (PMID 25576918, 2015). "That such a transition from monomeric actin to high molecular weight actin-positive complexes occurs during growth of tumors in vivo indicates a very important function for APLP2 in maintaining normal actin structure and function in the tumor microenvironment." (PMID 25576918, 2015). "Moreover, the APLP2 gene is related to tumour immunology as it regulates surface expression of the MHC class I molecules." (PMID 29377909, 2018). "Furthermore, we found positive APLP2 expression in a large proportion (38%) of paired primary tumor and liver metastasis samples from the same patients." (PMID 26840089, 2016). "Knockdown of APLP2 expression in tumors in vivo resulted in a significant slowing of tumor growth." (PMID 25576918, 2015). "The genes most positively associated with TMBIM6 expression, including LAMP2, APLP2, TMED10, PPAPDC2, ZNF652, and CTSB, are primarily involved in lysosomal and ER trafficking, membrane dynamics, and metabolic resilience—pathways that facilitate tumor survival under cellular stress conditions." (PMID 41516091, 2025). "Thus, pancreas-specific complete or partial loss of APLP2 did not entirely prevent tumor growth, although survival was prolonged by pancreas APLP2 deficiency." (PMID 33810510, 2021). "Intriguingly, some of these molecules are related to oncogenesis and tumour progression/metastasis, namely, HRAS, KRAS, TGFBR1, TGFBR2, RB1, ITGA6, ITGB4, mTOR, TSC2 and APLP2." (PMID 30258067, 2018). "APLP2-PIGR and LAM3-integrin-a3b1-complex interactions aid in cell adhesion and signal transduction, which may play critical roles in tumor progression." (PMID 40666516, 2025).
tumor (continued). "In addition, we performed qRT-PCR in vitro validation and found that APLP2,CDCA4 and VIM genes were significantly overexpressed in tumor tissues, and the expression of PTMA gene was also upregul XCated, but the difference lacked statistical significance." (PMID 38098487, 2023). "Two of 21 patients with an APLP2-negative primary tumor specimen had positive APLP2 expression in their liver metastases." (PMID 25576918, 2015). "Most of the significantly up-regulated genes were involved in cell cycle/mitosis/cell division (e.g., TTK, CENPF, NEK2), while many of those down-regulated were involved in cell adhesion/cell cycle arrest (e.g., ADRB2, APLP2, MACF1), consistent with a role of these genes in neoplasia development." (PMID 18297132, 2008). "In the present study, the three markers from the fibrosome with the highest reported predictive values (APLP2, BNIP3L, CD59) and an additional well-known fibrosis marker (DKK3) in renal and cardiac disease were investigated on protein expression level in primary tumor samples." (PMID 35796776, 2023).
gastrointestinal tumors (1 paper, 2020). "Along with amyloid precursor protein, APLP2 was frequently expressed in gastrointestinal tumors." (PMID 32257370, 2020).
APLP2 also shares sentences with these, for which no sentence is quoted: hyperopia (2 papers); adenocarcinoma (1); amyloid (1); anaplastic thyroid carcinoma (1); cardiac disease (1); colorectal cancer (1); COVID-19 (1); embryonal carcinoma (1); genetic disorder (1); germ cell tumor (1); glaucoma (1); glioma (1); Hepatic fibrosis (1); metastatic melanoma (1); neurodegenerative disease (1); neurodevelopmental disorder (1); neurological diseases (1); night blindness (1); ovarian cancer (1); retinal disorder (1); scrapie (1); Stroke (1); thyroid carcinoma (1); vitiligo (1).